DOCK10 (dedicator of cytokinesis 10)
Description:
Guanine nucleotide-exchange factor (GEF) that activates CDC42 and RAC1 by exchanging bound GDP for free GTP. Essential for dendritic spine morphogenesis in Purkinje cells and in hippocampal neurons, via a CDC42-mediated pathway. Sustains B-cell lymphopoiesis in secondary lymphoid tissues and regulates FCER2/CD23 expression.
Synonyms: KIAA0694; ZIZ3; DRIP2; Nbla10300
Tractability: Small molecule: a structure with a bound ligand is known. PROTAC: ubiquitination databases record sites on it; its protein half-life has been measured.
Gene: Protein-coding gene on chromosome 2 (224,765,090 to 225,042,468, reverse strand). Ensembl gene ENSG00000135905.
Subcellular location: Nucleus; Cytoplasm; Cell projection, dendritic spine
Subcellular location (Human Protein Atlas): Cytosol; Nucleoplasm
Pathways (Reactome):
Signal Transduction: CDC42 GTPase cycle; RAC1 GTPase cycle; RAC2 GTPase cycle; RAC3 GTPase cycle
Hemostasis: Factors involved in megakaryocyte development and platelet production
Gene Ontology:
Molecular function: protein binding; guanyl-nucleotide exchange factor activity; small GTPase binding
Biological process: regulation of cell migration; B cell homeostasis; dendritic spine morphogenesis; marginal zone B cell differentiation; positive regulation of GTPase activity; regulation of Rho protein signal transduction; regulation of postsynapse assembly; small GTPase-mediated signal transduction
Cellular component: cytoplasm; cytosol; extracellular exosome; membrane; nucleoplasm; nucleus; dendritic spine; glutamatergic synapse; postsynapse
Genetic constraint (gnomAD): Loss-of-function variants: 104 observed, 188.46 expected, observed/expected ratio (o/e) 0.55, 90% interval 0.47 to 0.65. The upper end of that interval is the gene's LOEUF score, 0.65, which puts it in group 2 of 6, group 1 being the genes least tolerant of losing a copy. Missense variants: 1,871 observed, 2,106.6 expected, observed/expected ratio (o/e) 0.89, 90% interval 0.85 to 0.92. Synonymous variants: 748 observed, 765.1 expected, observed/expected ratio (o/e) 0.98, 90% interval 0.92 to 1.04.
Homologues: Orthologues: chimpanzee DOCK10 (98% identical), macaque DOCK10 (98% identical), dog DOCK10 (94% identical), rabbit DOCK10 (93% identical), mouse Dock10 (93% identical), guinea pig DOCK10 (93% identical), pig DOCK10 (92% identical), rat Dock10 (91% identical), tropical clawed frog dock10 (73% identical), zebrafish dock10 (67% identical), Drosophila melanogaster Zir (25% identical), Caenorhabditis elegans F46H5.4 (20% identical), and 1 more. Paralogues in human: DOCK9 (52% identical), DOCK11 (48% identical), DOCK7 (27% identical), DOCK8 (27% identical), DOCK6 (26% identical), DOCK1 (14% identical), DOCK5 (14% identical), DOCK3 (14% identical), DOCK4 (14% identical), DOCK2 (13% identical).
Diseases named in the same sentence as DOCK10 in open-access papers:
DOCK10 is named in the same sentence as 21 diseases in open-access papers, as found by Europe PMC text mining. Sharing a sentence is not in itself a finding about the gene and the disease. The quoted sentences say what the papers report.
depression (3 papers, 2021 to 2023). "DOCK10 had a Cox regression OR of 1.9 (p = 3.93E−02) for predicting all future hospitalizations for depression in females." (PMID 33828235, 2021). "DOCK10 (dedicator of cytokinesis 10) has some prior human evidence in human blood from bipolars, and is decreased in expression in brain in an animal model of depression." (PMID 33828235, 2021). "The 6 top blood biomarkers with the strongest overall CFE for tracking and predicting both depression and mania, hence bipolar mood disorders, after the first four steps were NRG1, DOCK10, GLS, PRPS1, TMEM161B, and SLC6A4." (PMID 33828235, 2021). "A number of individual top biomarkers are known to be modulated by medications in current clinical use for treating depression, such as by lithium (NRG1, PRPS1, CD47), antidepressants (SLC6A4, DOCK10, NRG1, CD47) and the nutraceutical omega-3 fatty acids (GLO1, SLC6A4, CD47, GLS, HNRNPDL)." (PMID 33828235, 2021).
gastric cancer (3 papers, 2017 to 2026). A primary or metastatic malignant neoplasm involving the stomach. "One study identified cfDNA methylation biomarkers detectable in blood, reflecting tumor-derived signals from gastric cancer, such as DOCK10." (PMID 41516419, 2026). "The two loci (DOCK10 and FCN1-FCN2) replicated from CoGaPro1, and the 11 loci replicated from CoGaPro2 (CDK15, CROCC2-SNED1, TLR2-RNF175-SFRP2, WWC2, RELN, ZMYM5-ZMYM2, KLF12, SKAP1, CABLES2, and MIR630) gave further support for these genes being associated with a risk of CRC and gastric cancer." (PMID 41516419, 2026). "Furthermore, a 153 cfDNA methylation biomarker panel including DOCK10, CABIN1, and KCNQ5 was identified in a GC patient cohort, providing a novel method to diagnose early-stage gastric cancer." (PMID 36302755, 2022).
melanoma (3 papers, 2015 to 2021). A malignant, usually aggressive tumor composed of atypical, neoplastic melanocytes. "Loss of elongation was consistent with previous results by Gadea and coworkers, showing that Dock10 silencing induces the opposite effect, i.e., a change from rounded to elongated, in a melanoma cell line in three-dimensional environment." (PMID 25862245, 2015). "What we know about the role of Dock10 comes from a single study using gene silencing, showing Dock10 as a factor that sustains the rounded morphology and amoeboid-type movement in melanoma cells." (PMID 25862245, 2015). "Silencing of Dock10 expression leads to partial suppression of migration, and the simultaneous knock down of Dock10 and Rac1 suppresses migration completely, resulting in a decreased invasion of melanoma cells." (PMID 28507547, 2017). "DOCK10 activates Cdc42 which in turn leads to phosphorylation of MLC2 by PAK2, driving the amoeboid phenotype in melanoma." (PMID 34196668, 2021). "DOCK10, a Cdc42 GEF, is necessary for amoeboid motility while DOCK3 drives mesenchymal motility and invasion in melanoma cells through Rac1." (PMID 34196668, 2021). "However, deletion of DOCK10, PAK2 or N-WASP, which all contribute to amoeboid migration in melanoma cells, also resulted in an elongated morphology, implicating more Cdc42 pathways in mesenchymal migration." (PMID 34196668, 2021).
cardiac hypertrophy (2 papers, 2022 to 2025). "Global deletion of dedicator of cytokinesis 10 (DOCK10), a Rac GEF, resulted in more severe cardiac hypertrophy following AngII infusion and a greater reduction in p38 and JNK activation following acute PE treatment, however no direct effects on Rac1 activation were demonstrated." (PMID 41333012, 2025). "Thus, while the Dock10 KO did not induce cardiac hypertrophy, according to functional studies and fetal gene analysis, the ablation of this Rho GEF induced a mild dilated cardiomyopathy in unstressed mice." (PMID 36077014, 2022).
chronic lymphocytic leukemia (2 papers, 2017 to 2021). "Furthermore, we found that DOCK10 levels are increased by interleukin-4 (IL-4) in B-cell lymphoid neoplasms other than chronic lymphocytic leukemia (CLL) such as mantle cell lymphoma and diffuse large B-cell lymphoma." (PMID 34449554, 2021). "We ourselves have observed that DOCK10 was distributed between cytosol and nucleoplasm, but with higher levels in the latter, in a sample from a patient with chronic lymphocytic leukemia (CLL)." (PMID 34449554, 2021).
autism spectrum disorder (1 paper, 2014). A spectrum of developmental disorders that includes autism, and Asperger syndrome. "Less is known with respect to Dock10 and Dock11, although a rare Dock10 gene deletion is associated with autism spectrum disorders." (PMID 25309324, 2014).
diabetes (1 paper, 2023). "The DOCK10 association with diabetic atherosclerosis and its gene expression association with glucose in pancreatic islets suggest that the nonsynonymous meQTL SNPs in DOCK10 may link the gene’s methylation to T2D genetic factors, diabetes complications or mechanisms in islet cells." (PMID 37679740, 2023).
endometrial cancer (1 paper, 2021). Primary or metastatic malignant neoplasm involving the endometrium (mucous membrane that lines the endometrial cavity). "Of those not previously reported in IntOGen as mutational driver genes, all were found to be expressed in their corresponding cancer types and MED1 and DOCK10 were found to be mutated at >1 in endometrial cancers." (PMID 34313788, 2021).
lymphoid neoplasm (1 paper, 2021). A neoplasm composed of a lymphocytic cell population which is usually malignant (clonal) by molecular genetic and/or immunophenotypic analysis. "We found that IL-4 induces the expression of DOCK10 in lymphoid neoplasms such as mantle cell lymphoma and DLBCL, and we confirmed that IL-4 induces cytoplasmic levels of DOCK10 in CLL." (PMID 34449554, 2021). "DOCK10 expression is induced by IL-4 in CLL and normal B cells, but it is not known whether this occurs in other lymphoid neoplasms." (PMID 34449554, 2021).
Sepsis (1 paper, 2025). Sepsis is defined as life-threatening organ dysfunction caused by a dysregulated host response to infection. "Despite the discordance in expression trends for NUP160 and DOCK10 between bioinformatic predictions and our murine validation, their potential as sepsis biomarkers cannot be dismissed." (PMID 41394771, 2025). "Nonetheless, the mRNA expression of NUP160 and DOCK10 was elevated in LPS‐induced sepsis, which contradicts the findings from the bioinformatic analysis." (PMID 41394771, 2025). "The mRNA expression of NUP160 and DOCK10 was elevated in LPS‐induced sepsis, although the bioinformatic analysis indicated a contrary trend." (PMID 41394771, 2025). "Collectively, our bioinformatic and experimental findings indicate that ATP11B, RBBP7, DOCK10, and NUP160 are implicated in the pathogenesis and progression of sepsis." (PMID 41394771, 2025). "However, the mRNA expression of NUP160 and DOCK10 was upregulated in LPS‐induced sepsis, which was contrary to the bioinformatic analysis results." (PMID 41394771, 2025). "ATP11B, RBBP7, DOCK10, and NUP160 may play the major role in the occurrence and progression of sepsis." (PMID 41394771, 2025).
systemic lupus erythematosus (1 paper, 2023). An autoimmune multi-organ disease typically associated with vasculopathy and autoantibody production. "We made an intersection of the up-DPpGCs in Pla-KO1l3 with the genes for ‘systemic lupus erythematosus’ in the GWAS catalog and found three genes in common, namely, JAZF1, DOCK10, and BACH2." (PMID 38255187, 2023).
cancer (8 papers, 2015 to 2023). A tumor composed of atypical neoplastic, often pleomorphic cells that invade other tissues. "Focusing on confirmed carcinomas (n = 11) we found four genes which were mutated in more than one sample: PIK3CA, KRAS, ZZEF1 and DOCK10 were each mutated in two of the carcinomas (18% each)." (PMID 36635367, 2023). "DOCK10 is responsible for activation of the small GTPase Cdc42 during cell invasion and the association of Cdc42 with cancer and EMT has been widely documented." (PMID 29765546, 2018). "Several of the genes, such as Mmp8, Dock10, Hoxd3 and Fat3, have previously been reported to show mutation or altered expression in cancer and particularly metastasis." (PMID 28577549, 2017). "In cancer, DOCK10 (Dedicator Of Cytokinesis 10) is involved in the regulation of the epithelial to mesenchymal transition." (PMID 32704070, 2020). "In summary, using an inducible gene expression system in a cancer adherent cell line, we present here the first cellular model for studying Dock10 function by means of its overexpression." (PMID 25862245, 2015). "This exon is mapped to the DOCK10 gene which has been reported in several cancer studies." (PMID 28545391, 2017). "Previous study already identified a link between MAPK1, Dock10 and FoxO1 as a key signalling axis that incorporates MAPK1 signalling to promote cancer progression through induction of EMT, increased invasiveness and resistance to compression." (PMID 37131239, 2023).
tumor (6 papers, 2016 to 2026). "The co-expression network suggests that by influencing the interplay of CD86 and neural signal features such as LYN, PLXNC1, and DOCK10, it may mediate the interaction between neural signals and M1 macrophages, thereby affecting anti-tumor activity." (PMID 41147013, 2025). "Further investigation is necessary to determine whether SPANX-A/C/D or DOCK10 can also contribute to other key processes, such as intravasation and extravasation of tumor cells from blood vessels." (PMID 26895102, 2016). "Moreover, further significantly upregulated genes such as DOCK10, GPC6, and FSCN1 have been related to enhanced tumor cell migration and/or invasion." (PMID 35163822, 2022).
DOCK10 also shares sentences with these, for which no sentence is quoted: breast carcinoma (1 paper); cervical cancer (1); diabetic nephropathy (1); diffuse large B-cell lymphoma (1); dilated cardiomyopathy (1); heart failure (1); infection (1); mantle cell lymphoma (1).